EML1 (EMAP like 1)
Description:
Modulates the assembly and organization of the microtubule cytoskeleton, and probably plays a role in regulating the orientation of the mitotic spindle and the orientation of the plane of cell division. Required for normal proliferation of neuronal progenitor cells in the developing brain and for normal brain development. Does not affect neuron migration per se.
Synonyms: EMAP-1; EMAPL; EMAP; HuEMAP; ELP79; BH
Tractability: PROTAC: ubiquitination databases record sites on it; its protein half-life has been measured.
Gene: Protein-coding gene on chromosome 14 (99,737,693 to 99,942,060, forward strand). Ensembl gene ENSG00000066629.
Subcellular location: Cytoplasm; Cytoplasm, perinuclear region; Cytoplasm, cytoskeleton
Gene Ontology:
Molecular function: microtubule binding; protein binding; tubulin binding; calcium ion binding
Biological process: brain development; microtubule cytoskeleton organization; mitotic spindle organization; neuroblast proliferation
Cellular component: microtubule; microtubule cytoskeleton; cytoplasm; cytosol; microtubule associated complex; mitotic spindle; mitotic spindle midzone; mitotic spindle pole; cytoskeleton; perinuclear region of cytoplasm
Genetic constraint (gnomAD): Loss-of-function variants: 26 observed, 100.14 expected, observed/expected ratio (o/e) 0.26, 90% interval 0.19 to 0.36. The upper end of that interval is the gene's LOEUF score, 0.36, which puts it in group 1 of 6, group 1 being the genes least tolerant of losing a copy. Missense variants: 690 observed, 976.96 expected, observed/expected ratio (o/e) 0.71, 90% interval 0.66 to 0.75. Synonymous variants: 313 observed, 360.66 expected, observed/expected ratio (o/e) 0.87, 90% interval 0.79 to 0.95.
Gene-disease validity (ClinGen):
ClinGen rates the evidence that EML1 causes each of these diseases.
band heterotopia of brain (autosomal recessive): Definitive.
Homologues: Orthologues: chimpanzee EML1 (99% identical), macaque EML1 (97% identical), dog EML1 (97% identical), mouse Eml1 (96% identical), pig EML1 (95% identical), rat Eml1 (94% identical), guinea pig EML1 (94% identical), rabbit EML1 (90% identical), tropical clawed frog eml2 (85% identical), zebrafish eml1 (79% identical). Paralogues in human: EML4 (55% identical), EML2 (54% identical), EML3 (49% identical), EML6 (34% identical), EML5 (34% identical), WDR90 (22% identical), CFAP44 (19% identical), CFAP251 (18% identical), CFAP52 (15% identical).
Diseases named in the same sentence as EML1 in open-access papers:
EML1 is named in the same sentence as 21 diseases in open-access papers, as found by Europe PMC text mining. Sharing a sentence is not in itself a finding about the gene and the disease. The quoted sentences say what the papers report.
Usher syndrome (3 papers, 2023 to 2024). A syndromic diseae characterized by the association of sensorineural deafness (usually congenital) with retinitis pigmentosa and progressive vision loss. "The EML1 (echinoderm microtubule-associated protein-like 1) gene is linked to deafness and blindness in Usher syndrome type 1." (PMID 38440980, 2024). "EML1 is a microtubule-associated protein-like gene in which rare mutations are linked to Usher syndrome (USH), a group of genetic disorders manifesting congenital deafness, retinitis pigmentosa, and vestibular dysfunction." (PMID 37398472, 2023).
band heterotopia (2 papers, 2021 to 2022). "Thus, the EML1-associated band heterotopia -phenotype seems to be a very rare neurological condition." (PMID 34211111, 2021).
heterotopia (2 papers, 2021 to 2022). "Only six unrelated EML1-associated heterotopia-affected families were reported so far." (PMID 34211111, 2021). "In this study we identify a new gene for subependymal and subcortical heterotopia, revealing a de novo Disks large-associated protein 4 (DLGAP4) frameshift variation in a patient with unilateral heterotopia and polymicrogyria, resembling the EML1 phenotype." (PMID 35585091, 2022).
Hydrocephalus (2 papers, 2020 to 2022). Hydrocephalus is an active distension of the ventricular system of the brain resulting from inadequate passage of CSF from its point of production within the cerebral ventricles to its point of absorption into the systemic circulation. "Homozygous HeCo mice carrying a spontaneous Eml1 mutation have been found to exhibit a subcortical heterotopia in the brain with associated hydrocephalus and cognitive impairment." (PMID 35190581, 2022).
epilepsy (1 paper, 2023). A brain disorder characterized by episodes of abnormally increased neuronal discharge resulting in transient episodes of sensory or motor neurological dysfunction, or psychic dysfunction. "In addition, we identified a number of genes altered in PTE+ astrocytes that are known to be involved in differentiation, migration, and cell morphology, of which several are associated with epilepsy (i.e., Eml1, Map2, Map1b, Sema3f, and Ptn)." (PMID 37174647, 2023).
polymicrogyria (1 paper, 2022). A developmental brain abnormality characterized by an excessive amount of small convolutions on the surface of the brain and cognitive dysfunction. "Additionally, individuals with mutations in EML1, exhibit SBH, megalencephaly, polymicrogyria (section “Polymicrogyria”), and agenesis of corpus callosum." (PMID 36340790, 2022).
tumor (4 papers, 2017 to 2025). "Our findings describe, for the first time, a tumor setting where EML1 may act as a novel gene for the stem cell-like phenotype of cancer cells." (PMID 40696387, 2025). "Results confirmed that BLCAP, EML1, FOSL2, ADNP and FRMD3 were deregulated in the same way among the xenografts, FFPE and OCT tumour samples." (PMID 30592148, 2019).
cancer (1 paper, 2025). A tumor composed of atypical neoplastic, often pleomorphic cells that invade other tissues. "This led to pSTAT3-mediated activation of cancer stemness genes (IGFN1, EML1, and SRGN), contributing to Adriamycin resistance." (PMID 40696387, 2025).
EML1 also shares sentences with these, for which no sentence is quoted: genetic disorders (3 papers); glioma (3); retinitis pigmentosa (2); Blindness (1); brain tumor (1); COVID-19 (1); deafness (1); Intellectual disability (1); Lissencephaly (1); lymphopenia (1); neuroblastoma (1); neuronal migration disorder (1); Usher syndrome type 1 (1).